CDK2 (cyclin dependent kinase 2)
Diseases named in the same sentence as CDK2 in open-access papers (continued):
Sharing a sentence is not in itself a finding about the gene and the disease.
breast cancer (continued). "In addition, we selected two patients with different MAFG-AS1 expressions and the immuno-histochemical staining of breast cancer tissues showed that the expression of CDK2 and ki-67 was consistent with the MAFG-AS1 expression, indicating that MAFG-AS1 was related to proliferation." (PMID 33098638, 2020). "Notably, phosphorylated CDK-2 has been indicated as a biomarker for aggressive breast cancer." (PMID 28650989, 2017). "Because the breast cancer cell lines overexpressed cyclin D1, and cyclin A protein levels were elevated following irradiation, we tested whether knockdowns of their respective kinase partners CDK4 and CDK2 might alter the relative radioresistance of various breast cancer cell lines." (PMID 23886499, 2013). "Moreover, primary breast cancers harbouring CCNE1 amplification were found to have higher levels of CDK2 mRNA expression, adjusted for proliferation using the mRNA levels of CCNB1, than breast cancers devoid of CCNE1 amplification (P = 0.02789, t-test, data not shown)." (PMID 22433433, 2012). "Taken together, these results demonstrate that breast cancer cells harbouring CCNE1 gene amplification are dependent on CDK2 expression and kinase activity for their survival and suggest that CCNE1 amplification may constitute a potential biomarker of sensitivity to CDK2 inhibitors." (PMID 22433433, 2012). "In fact, several studies have shown that E2 controls the Cyclin D1, c-Myc, CDK2, CDK4, and CDK inhibitors in MCF-7 breast cancer cells, thus promoting the progression from the G1 to S phase of the cell cycle." (PMID 40801565, 2025). "Using preclinical HR+ human breast cancer models with acquired resistance to CDK4/6i, we demonstrate that maintaining CDK4/6i therapy, either alone or combined with CDK2 inhibitors (CDK2i), slows the growth of resistant tumors by prolonging G1 progression." (PMID 41459763, 2025). "Dinaciclib, a drug that targets CDK1, CDK2, CDK5, and CDK9, has demonstrated efficacy in the treatment of breast cancer by reducing the expression of stem cell markers and decreasing cancer cell viability." (PMID 40004024, 2025). "In research, the lncRNA TROJAN led to CDK2 upregulation by linking to NKRF and blocking its inhibition on RELA/p65, so contributing to the decreased response of ER+ breast cancer cells to CDK4/6is." (PMID 40244377, 2025). "This phase I/IIa study evaluated the safety, PK, pharmacodynamics, and preliminary antitumor activity of the first-in-class CDK2/4/6i PF-06873600, alone and in combination with ET, in patients with HR+/HER2− advanced breast cancer or mBC." (PMID 40243688, 2025). "While TCGA has revolutionized cancer biomarker discovery, exemplified by studies identifying SCN3B in glioma, CDK2 in glioma prognosis, AIMP1/CNIH4 in head-neck squamous carcinoma, and RAD50 in breast cancer, its limitations must be acknowledged." (PMID 40860678, 2025). "This is primarily due to the reduction in expression of CDK2, CDK4, CDK6, and Akt proteins, which enhances the sensitivity of resistant breast cancer cells to tamoxifen." (PMID 40283888, 2025). "We also describe the effects of INX-315 in preclinical models of CCNE1-amplified cancer and use the compound to dissect out the roles of CDK2 and CDK4/6 in treatment-naïve and therapy-resistant luminal breast cancers." (PMID 38047585, 2024). "We show that although the proliferation of luminal breast cancers is initially CDK4/6-dependent, CDK2 activity can overcome persistent CDK4/6 inhibition, eventually restoring Rb phosphorylation to a level that facilitates cellular entry into S-phase." (PMID 38047585, 2024).
breast cancer (continued). "Here, we describe the creation of a novel, potent, and selective inhibitor of CDK2 and characterize its activity in models of CCNE1-amplified cancer and CDK4/6i–resistant luminal breast cancer." (PMID 38047585, 2024). "Cyclin-dependent kinase 2 (CDK2) is thought to play an important role in driving proliferation of certain cancers, including those harboring CCNE1 amplification and breast cancers that have acquired resistance to CDK4/6 inhibitors (CDK4/6i)." (PMID 38047585, 2024). "In breast cancer, CDK1, CDK5, and CDK20 are overexpressed, while CDK2 and CDK6 are decreased, with high expression correlating with poor prognosis." (PMID 39567714, 2024). "Genes such as APP, CDK1, CDK2, and ESR1 were the most frequently observed in this list and have been previously extensively characterized in breast cancer." (PMID 38378612, 2024). "Previous studies involving leukemia and breast cancer models have revealed that CDK1 relies more on CDK7-mediated activation activity and stability, while other CDK-activating kinases can also regulate CDK2, in addition to CDK7." (PMID 37507802, 2023). "Our previous study demonstrated that IGFBP-3 induced G1 cell cycle arrest by inhibiting cyclin D1, cyclin D3, cyclin E, cyclin A, CDK2, CDK4, total and phospho-pRb, and increasing p21 and p16 in MCF-7 breast cancer cells." (PMID 37253773, 2023). "When 14-3-3 sigma was overexpressed, Western blot assay presented increased protein expression of P21 and decreased levels of cyclin D1, CDK2 and CDK6 in breast cancer cells." (PMID 35890172, 2022). "Isoangustone A dose-dependently decreased DNA synthesis and induced G1 phase arrest in human prostate and mouse breast cancer cells, reduced the levels of CDK2 and CDK4 as well as cyclin A and cyclin D1 proteins, and also induced a decrease in CDK2 activity." (PMID 36278690, 2022). "We found that decreased expression of circ_6014 decreased the protein expression levels of PCNA, CDK2/CCNE1, and CDK4/6/CCND1, and overexpression of circ_6014 increased the expression of these proteins in breast cancer cells (Student’s t test, p < 0.05)." (PMID 35383130, 2022). "Higenamine enhanced the anticancer effects of cucurbitacin B in breast cancer by suppressing the interaction of protein kinase B (AKT) and cyclin-dependent kinase 2 (CDK2)." (PMID 35662730, 2022). "We found that the mechanism between SFN and CDK2 in subnetwork 16 was supported by observations that SFN is a frequently hypermethylated gene emerging as a new inhibitor of CDK2 in breast cancer cells." (PMID 36418365, 2022). "Our differential expression analysis of CDK2 and CDK4 expression profiles revealed that both CDK2 and CDK4 are overexpressed in breast cancer tumors compared to adjacent normal tissues." (PMID 34421361, 2021). "Recently, we found that co-targeting CDK2, CDK6, and ER signaling inhibits the growth of ER+/HER2− breast cancer cells resistant to combined CDK4/6i and ET, supporting the use of this triple combination as a novel therapeutic strategy." (PMID 34771560, 2021). "Altogether, our bioinformatics analysis of clinical information from breast cancer patients strongly suggested that CDK2 and CDK4 are biomarkers of tumor progression, metastasis, and prognostic and therapy responses in breast cancer." (PMID 34421361, 2021). "To evaluate the clinical relevance of CDK2 and CDK4 in breast cancer, we analyzed CDK2- and CDK4-related clinical information of breast cancer patients from TCGA pan-cancer database." (PMID 34421361, 2021). "To explore the role of ACTL6A/MYC/CDK2 in the progression of TNBC, we detected these genes in breast cancer tissues and cell lines." (PMID 33541412, 2021).
breast cancer (continued). "In contrast, the potent cyclin dependent kinase inhibitor p21 which binds to and inhibits the activity of cyclin-CDK2, -CDK1, and -CDK4/6 complexes, was dose-dependently upregulated in both breast cancer cell lines and to a lesser extend in MCF-10A." (PMID 32292575, 2020). "Although selective CDK4/6 inhibition results in less toxicity, a huge challenge is that breast cancer (including basal-like breast cancer) adapt quickly to CDK4/6 inhibition, while inhibiting CDK2 simultaneously is an effective solution." (PMID 33246450, 2020). "To investigate the clinical correlation among TROJAN, CDK2 and the proliferation marker MKI67, we performed qRT-PCR to measure their expression in ER+ breast cancer specimens." (PMID 32393270, 2020). "The Lnc712/HSP90/Cdc37 complex regulated cyclin-dependent kinase 2 (CDK2) activation and then triggered breast cancer cell proliferation." (PMID 31892853, 2020). "Several recent studies reported that SMAD2 promoted the tumor progression by upregulating the CDK2, CDK4, and cyclin E in metastatic breast cancer cells." (PMID 33330073, 2020). "Amongst the regulatory pathways, ERα and CDK2 were proliferation-related indicators, which fully verified the function of MAFG-AS1 in ER+ breast cancer." (PMID 33098638, 2020). "CDK2 inhibitor can selectively target CD44+CD24- subpopulation and restores chemo-sensitivity in breast cancer." (PMID 31120927, 2019). "We observed that transfection with SALL1 significantly increased the gene expressions of Cyclin A2, Cyclin B1, Cyclin E1, CDK2 and CDK4 in breast cancer MDA cells, which are important for checkpoint regulation in G1-S transition and S phases." (PMID 29625565, 2018). "Consistent with the biochemical results, our immunohistochemical analysis of breast cancer tissue microarrays showed significant positive correlation of RHBDD1, p-Akt and CDK2 protein levels, indicating that these proteins have clinicopathological relevance." (PMID 30286765, 2018). "Immunohistochemistry was performed to evaluate RHBDD1 expression in 116 breast cancer tissue and 39 adjacent normal tissue and expression of RHBDD1, phospho-Akt (p-Akt) and cyclin-dependent kinase 2 (CDK2) in the same 84 breast cancer specimens." (PMID 30286765, 2018). "In breast cancer estrogen can independently regulate the expression and function of the proto-oncogene c-Myc followed by a rapid activation of the G1 CDK, CDK2, to induce cell cycle progression." (PMID 28423577, 2017). "4-((6-(Cyclohexylmethoxy)-9H-purin-2-yl)amino)benzenesulfonamide (NU6102) is a low-nanomolar inhibitor of CDK2 (Ki CDK2 = 6 nM), but has a modest GI50 (8 μM) against human MCF-7 breast carcinoma cells." (PMID 26320860, 2015). "We then inhibited CDKs including CDK4/6, CDK2 and CDK1 individually using either RNAi or small molecule inhibitors, and compared sensitivity to CDK inhibition with MYC dependence in breast cancer cells." (PMID 24444383, 2014). "Thus there is a positive feed-back loop between cyclin-A/Cdk2 and Aurora-A pathways in the development of centrosome amplification in breast cancer cells which may be which may provide additional approaches to target drug resistant breast cancer patients." (PMID 25051360, 2014). "In this study we used an RNAi approach to identify MYC-dependent breast cancer cell lines and then inhibited CDKs including CDK4/6, CDK2 and CDK1 individually by either RNAi or small molecule inhibitors in both MYC-dependent and MYC-independent cells." (PMID 24444383, 2014). "There are studies suggesting association between Her2 over-expression and CA in breast tumors, and one showing that mammary tumors in MMTV-Neu mice display CA, but the molecular contribution of Cdk2 and Cdk4 to Her2/Neu-mediated CA has yet to be elucidated." (PMID 23776583, 2013). "Luminal breast cancers harboring elevated CCND1 would contain both CCND1/CDK4 and CCND1/CDK2 complexes." (PMID 23390492, 2013).
breast cancer (continued). "It had been confirmed that GLK triterpenes both concentration- and time-dependently mediate G1 cell cycle arrest and significantly decrease the protein level of CDK2, CDK6, cycle D1, p-Rb and c-Myc in MCF-7 human breast cancer cells." (PMID 23966082, 2013). "In previous study, the genes (CDK1, CDK2 and CDK4) were dysregulated in breast cancer, ovarian cancer, colon cancer, hepatocellular carcinoma, thyroid carcinoma, and lung cancer." (PMID 24386425, 2013). "In breast cancer cells, gene knockdown has been shown to decrease CCNE1 expression and Cyclin E1/CDK2 activity." (PMID 21103391, 2010). "In this report we demonstrate that metformin-sensitive breast cancer cells arrest in G0/G1 due to activation of AMPK, downregulation of cyclin D1, and enhanced binding of CDK2 by p27Kip1 and p21Cip1." (PMID 19046439, 2008). "Although no specific inhibitors of CCNE2 currently exist, CDK2 inhibitors have shown efficacy in suppressing the proliferation of CCNE2‐overexpressing breast cancer cells." (PMID 41562186, 2026). "While CDK4/6 inhibitors have been effectively combined with ICI for the treatment of breast cancer, this combination with or without CDK2 inhibition has not yet been demonstrated to be clinically effective for metastatic melanoma." (PMID 40904502, 2025). "The CDK2 selective catalytic inhibitor INX-315 induced a potent growth arrest in the CDK2-addicted models, which closely mirrors the effect of palbociclib in CDK4-addicted ER+ breast cancer models." (PMID 39924553, 2025). "Thus, the synergistic antiproliferative effect of the combined inhibition of CDK2 and CDK4/6 in breast cancer can overcome acquired resistance to CDK4/6 inhibitors by enhancing senescence." (PMID 40904502, 2025). "Similarly, in CDK4-addicted HR + /HER2- breast cancer models (MCF7 and CAMA1), the impact on cell cycle proteins following CDK4 depletion was more pronounced than CDK2 depletion." (PMID 39924553, 2025). "A previous study revealed the formation of a noncanonical cyclin D–CDK2 complex in HR+ breast cancer cells, leading to resistance through alternative CDK2 activation." (PMID 39930131, 2025). "Consistent with these prior findings, we did not observe a significant impact on the viability of MCF7 breast cancer cells (known low CDK2 activity) upon POLE suppression." (PMID 40760094, 2025). "This includes Palbociclib, Abemaciclib, and Ribociclib, clinically approved CDK4/6 inhibitors commonly used in treating breast cancers, as well as Atirmociclib, a novel CDK4-selective inhibitor, and two CDK2 inhibitors in clinical trials, Tagtociclib and INX-315." (PMID 41279360, 2025). "CDK2, a critical regulator of the cell cycle, is a promising drug target, especially in cancers with cyclin E1 protein overexpression, including HR+/HER2− breast cancer resistant to CDK4/6 inhibitors." (PMID 39184861, 2024). "The CDK2 inhibitor INX-315 induces cell cycle arrest and therapy-induced senescence, thereby controlling the growth of CCNE1-amplified cancers and CDK4/6 inhibitor-resistant breast cancers, which together supports future clinical development." (PMID 38047585, 2024). "Second, acquired resistance to CDK4/6 inhibition in luminal breast cancers may be driven by cyclin E/CDK2 activity (facilitating S-phase entry despite CDK4/6 blockade), providing rationale for studying the inhibition of CDK2 in these tumors as well." (PMID 38047585, 2024). "Indeed, it has been shown that activated GR binds to and represses the enhancer regions of the ER-mediated cell cycle genes’ (e.g., CCND1, CDK2, and CDK6) in ER+ breast cancer cells." (PMID 39519365, 2024).
breast cancer (continued). "Meanwhile, inhibiting miR-125b using LNA inhibitor in the miR-125b-high MDA-MB-231 and MDA-MB-415 breast cancer cells resulted in increased E2F3, CDK2, CCNA2 and Bak1 protein expression and increased phosphorylation of Rb, which is indicative of increased G1-S progression with miR-125b inhibition." (PMID 38093346, 2023). "Presently, there is no CDK2 inhibitor approved for the treatment of breast cancer, but several novel drugs are currently undergoing pre-clinical evaluation against breast cancer." (PMID 35884422, 2022). "CDK2 and CDK4 reduction arrest the G1 cell-cycle in MCF-7 human breast cancer cells." (PMID 35216267, 2022). "In addition, western blotting indicated that miR-885-3p suppressed the progression of breast cancer cells by downregulating the expression level of PCNA and the expression levels of CDK2/CCNE1 and CDK4/6/CCND1 (Student’s t test, p < 0.05)." (PMID 35383130, 2022). "Transcriptomic analyses of primary breast cancers confirmed higher cyclin E/CDK2 expression in TNBC compared with non-TNBC." (PMID 35884422, 2022). "Importantly, Cyclin E-CDK2 complexes drive cell-cycle progression (S-phase entry) and the activation of CDK2 represents one of the mechanisms of CDK4/6i resistance in breast cancer." (PMID 35546399, 2022). "In ER+ breast cancer, low expression of p21 leads to promoted cell cycle because p21 failed to inhibit CDK2‐cyclin E complex." (PMID 34761877, 2021). "Moreover, we analyzed the mRNA expression of ACTL6A and CDK2, the protein expression of MYC in public human breast cancer datasets from TCGA." (PMID 33541412, 2021). "Alternatively, the expression of the estrogen receptor on palbociclib-resistant breast cancer cells has been described to sensitize them towards adenoviral replication and oncolysis due to their low antiviral IFN response and increased cyclin-dependent kinase-2 activation." (PMID 34696274, 2021). "Indeed, miR-122-5p inhibitors indicated a major effect of miR-122-5p on the regulation of key antiapoptotic proteins Bcl-2 and cyclin-dependent kinases (CDK2, CDK4 and CDK6) in drug-resistant breast cancer cells in response to RSV." (PMID 34444715, 2021). "Correlation analyses also indicated that CDK4 expression was positively correlated with expressions of CDK2 and CDK6 in liver cancer, lung cancer, prostate cancer, pancreatic cancer, melanoma, head and neck cancer, glioblastoma, breast cancer, and cervical cancer cohorts (r = 0.06~0.69)." (PMID 33668805, 2021). "Furthermore, 9-cis RA decreased cyclin D1 and D3 expression levels as well as the expression and activity of CDK2 and CDK4 in breast cancer cells." (PMID 34444715, 2021). "The serine/threonine protein kinases CDK2 and GSK-3β are key oncotargets in breast cancer cell lines, therefore, in the present study three series of oxindole-benzofuran hybrids were designed and synthesised as dual CDK2/GSK-3β inhibitors targeting breast cancer (5a–g, 7a–h, and 13a–b)." (PMID 33327806, 2021). "Many of the proposed resistance mechanisms such as Rb loss or CDK2 activation are not easily amenable to targeted therapeutic interventions; however, the PI3K pathway activation in breast cancer has been successfully targeted with small molecule inhibitors." (PMID 32795346, 2020). "As a clinical prognostic factor in luminal breast cancer patients, MAFG-AS1 could up-regulate CDK2 by sponging miR-339-5p and accelerating the G1/S phase transition." (PMID 33098638, 2020). "Studies indicated that the inhibition of CDK2 and CDK4 enhanced autophagy in breast cancer cells." (PMID 30769922, 2019). "Pairwise comparison using Spearman’s rank correlation test revealed that the protein level of RHBDD1 and p-Akt was remarkably positively correlated in breast cancer tissue (Spearman’s ρ = 0.437; p = 3.245e-05), as was that of RHBDD1 and CDK2 (Spearman’s ρ = 0.386; p = 0.0003)." (PMID 30286765, 2018).